OXTR (oxytocin receptor)
Diseases named in the same sentence as OXTR in open-access papers (continued):
Sharing a sentence is not in itself a finding about the gene and the disease.
autism (continued). "OXTR is just one of several genes that have been linked to autism etiology." (PMID 23226454, 2012). "It is suggested that polymorphic variation at the oxytocin receptor gene (rs2254298) is associated with sociability, amygdala volume and differential risk for psychiatric conditions including autism, depression and anxiety disorder, depending on the quality of early environmental experiences." (PMID 22510359, 2012). "We are reluctant to attach too much significance to this finding because it could easily be due to sampling variation, but we do note that two recent studies reported that this and another SNP in the 5′-region of OXTR were associated with autism." (PMID 20585395, 2010). "Furthermore, a field of interest is the identification of polymorphisms and epigenetic modifications of the oxytocin receptor gene; there is evidence that both appear to be associated to a lower gene expression in the temporal cortex and cerebellar areas in patients with autism and SZ." (PMID 34299076, 2021). "Changes in the methylation status of the OXTR promoter have also been associated with altered expression of the receptor in the postmortem brains of persons with autism, suggesting that epigenetic mechanisms may also be complicit in pathogenic regulation of OXTR expression in ASD." (PMID 22958480, 2012). "Aberrations in OXTR expression within the hippocampus have been documented in the Magel2 mouse model of autism." (PMID 39277552, 2025). "Previous work from members of our group reported dysregulation in oxytocin receptor (OXTR) binding in postmortem tissue from the basal forebrain in donors with autism compared to unaffected control donors." (PMID 41255981, 2025). "One of the processes modulating the efficiency of the expression of OXTR is epigenetic modification, especially DNA methylation, which can probably affect the course of autism." (PMID 36835321, 2023). "Connections of various dysfunctions of OXTR and the oxytocin system with not only autism, depression, and schizophrenia, but also different mental disorders were reported." (PMID 36835321, 2023). "Early evidence for the connection between OXTR and autism came from observations that significant changes in plasma oxytocin OXT levels occur in affected patients." (PMID 36835321, 2023). "This conclusion has been recently corroborated by results of post-mortem studies indicating that the levels of OXTR in the brains of females with autism were lower than in autistic males and healthy individuals." (PMID 36835321, 2023). "Studies have shown that oxytocin receptor knockout mice show autism related behavior defects, while the supplement of exogenous oxytocin can improve this defect." (PMID 35937893, 2022). "Some genome-wide linkage studies show that oxytocin receptor gene is a reasonable candidate gene for autism." (PMID 35937893, 2022). "Postmortem human brain tissue specimens revealed that females with autism had significantly lower levels of oxytocin receptor expression than did males with autism or typically developing males and females." (PMID 35858106, 2022). "Postmortem human brain tissue specimens were processed for OXTR autoradiography from four groups: males with autism, females with autism, typically developing (TD) males and TD females." (PMID 35858098, 2022). "Others already reported reduction in OXTR gene expression in patients with mental disorders, for instance a decrease in autism cases and in schizophrenia patients in brain regions involved in social cognition." (PMID 35361281, 2022). "This study assessed the clinical utility of blood OXT serum levels and the OXT receptor (OXTR) genotype as biomarkers of autism and its severity in a pediatric population in Iraq." (PMID 35316293, 2022). "Like OXTR, polymorphisms of the genes coding the subunits of the GABA A receptor were reported to be correlated with altruism and autism." (PMID 30633779, 2019).
autism (continued). "This equivalence establishes the validity of the theoretical model and interprets the Stanford data as indicating the significance of the oxytocin receptor in the severity of autism as measured by the NEPSYS theory of mind scores used in the Stanford study." (PMID 31827587, 2019). "KCC2 down-regulation in the hippocampus delays postnatal GABA shift in oxytocin receptor knockout mouse model of autism." (PMID 31868588, 2019). "Their findings show an OXTR-dependent change in the connectivity of the reward circuitry in children with autism during resting state." (PMID 30918622, 2019). "The relationship between Ss′ and Ru′, namely Ss′ = Ru′, alludes to the importance of the oxytocin receptor system in the development of autism." (PMID 31827587, 2019). "One other previous study combined imaging and genetics to study OXTR in autism, and that study focused on the reward circuitry and especially the nucleus accumbens (NAcc)." (PMID 30918622, 2019). "The findings suggest a neurogenetic mechanism by which OXTR-dependent activity within the rSMG is related to the aetiology of autism." (PMID 30918622, 2019). "This is one of the first studies, to our knowledge, to incorporate OXTR genotype and brain function data in order to better understand the biological underpinnings of social cognition and cognitive empathy in autism." (PMID 30918622, 2019). "The current investigation aimed to understand the links between oxytocin receptor genotype, brain activity in response to an explicit cognitive empathy task, and autism." (PMID 30918622, 2019). "The agreement between the Stanford findings following the mathematical operations on them indicated in the paper and the theoretical model proposed therein strongly argue for the significance of the oxytocin receptor in autism." (PMID 31827587, 2019). "It seems very likely that one of the factors which plays a role in the pathogenesis of autism is the oxytocin receptor system especially in early development." (PMID 30057594, 2018). "The finding that the microRNAs that can target OXTR are upregulated in the brain of individuals with autism suggests that molecular pathways responsible for social behaviors are directly targeted by microRNAs in the brain." (PMID 26273428, 2015). "A profound impairment in social recognition in oxytocin receptor-knockout mice has been shown, indicating an important role played by these peptides in social and affective disorders, including autism and anxiety disorders." (PMID 24400970, 2014). "Elevated methylation of the CpG site 934 bp upstream of the translation initiation site is correlated with decreased mRNA level of the OXTR gene in the brain cortex tissue of autism cases." (PMID 24523928, 2014). "Although investigated in a small sample, these findings suggest functional importance of OXTR promoter methylation with regard to gene regulation, and possibly the etiology of autism." (PMID 23734094, 2013). "Whereas a number of studies have shown associations between variants of OXTR and autism spectrum disorder, we are aware of only one investigation assessing the role of differential methylation of OXTR in autism." (PMID 23734094, 2013). "In a next step, analyses were extended beyond this family, and OXTR methylation in DNA from peripheral blood mononuclear cells (PBMCs) was investigated in 20 individuals with autism and 20 matched normotypical controls." (PMID 23734094, 2013). "Hypermethylation of the same segment of the human OXTR correlates with low expression levels of the gene in postmortem brain tissues of individuals with autism." (PMID 23441222, 2013). "Adding to this, combined analysis of linkage data from two independent genome-wide screens of the Autism Genetic Resource Exchange (AGRE) and a large Finnish autism cohort identified OXTR among four susceptibility loci for autism." (PMID 22958480, 2012). "This speaks against a simple relationship of amygdala size with autism that is mediated by the OXTR genotype." (PMID 22510359, 2012).
autism (continued). "OXTR has been discussed as a candidate gene for autism spectrum vulnerability, but until to date only few studies have investigated variations of oxytocinergic system genes in schizophrenia." (PMID 23284802, 2012). "Polymorphic variation at the OXTR is a candidate for differential susceptibility to environmental contingencies, which, if associated with adversity during early childhood or even the prenatal period, may result in a greater risk of developing psychopathologies such as autism." (PMID 22510359, 2012). "It is worth mentioning here that FOXP2 protein dramatically down-regulates CNTNAP2, a strong candidate gene for autism, whereas OXT gene encodes the neuropeptide binding the oxytocin receptor (OXTR), another strong candidate gene for autism." (PMID 20885821, 2010). "Based on the strength of the novel deletion of OXTR and the previous data implicating OXTR in the development of autism, we focused further copy number analysis on the 3p25.3 deletion by screening other members of the proband's family." (PMID 19845972, 2009). "The impact of this epigenetic mark on OXTR expression was supported by analysis of the corresponding mRNA from the temporal cortex of autism cases matched for age and sex and controls." (PMID 19845972, 2009). "Together, these data provide further evidence for the role of OXTR and the oxytocin signaling pathway in the etiology of autism and, for the first time, implicate the epigenetic regulation of OXTR in the development of the disorder." (PMID 19845972, 2009). "Associated with the increase in methylation of these CpG dinucleotides is our finding that OXTR mRNA showed decreased expression in the temporal cortex tissue of autism cases matched for age and sex compared to controls." (PMID 19845972, 2009). "For instance, since the VP is part of the mesolimbic reward pathway, a reduced ability of OXT to activate OXTR in that area may contribute to a reduced experience of social reward or social motivation in autism." (PMID 41255981, 2025). "The gPPI analyses using a seed-to-whole brain approach (seeds defined according to the MVPA analyses) revealed no significant (pFWE < 0.05) FCs associated with trait autism during processing of specific emotional faces irrespective of OXTR genotype." (PMID 38553454, 2024). "When a combined analysis of the primary genome scan data from the Autism Genetic Resource Exchange and samples derived from Finnish patients suffering from autism was performed, OXTR was identified as a candidate gene responsible for autism if present in a mutant form." (PMID 36835321, 2023). "Moreover, significantly changed densities of OXTR in the human basal forebrain and midbrain were reported in the postmortem brain tissue from individuals with autism, relative to the controls." (PMID 36835321, 2023). "It was proposed that animal models should be useful in studies on the role of OXTR in autism." (PMID 36835321, 2023). "The hypothesis on the involvement of OXTR dysfunction in the development of autism has been also proposed on the basis of different kinds of genetic analysis." (PMID 36835321, 2023). "We found that females with autism had significantly lower levels of OXTR than the other groups." (PMID 35858098, 2022). "Here, we explore whether differences in OXTR can be identified in the dopaminergic SN pars compacta of individuals with autism." (PMID 35858098, 2022). "Indeed, some clinical studies reported oxytocin receptor epigenetic variations or modifications in the circulating levels of OXT in individuals affected by autism and conduct disorders." (PMID 34068684, 2021). "OXTR and the oxytocin signaling pathway have important roles in the etiology of autism." (PMID 33712060, 2021). "This is one of the first studies to investigate OXTR and brain function in autism." (PMID 30918622, 2019).
autism (continued). "The aim of the current study was to better understand the complex interaction between oxytocin genotype, brain function, and autism, by integrating OXTR genotype and brain imaging data in a sample of adolescents (aged 12.01–18.53 years) with and without an autism diagnosis." (PMID 30918622, 2019). "OXTR is significantly overexpressed in the autism brain samples (p = 0.005)." (PMID 26273428, 2015). "Nonetheless, we may hypothesize that in the autism brain, attempts to increase OXTR protein levels, and downstream social behaviors, are being inhibited by miR-21-5p, thereby exacerbating the autism phenotype." (PMID 26273428, 2015). "We present evidence that microRNA dysregulation occurs in the brain of individuals diagnosed with autism spectrum disorders and that the dysregulated microRNAs target biological pathways and specific genes that are highly relevant to the biology of autism, including the OXTR gene." (PMID 26273428, 2015). "Of importance, the finding that miR-21-5p expression is negatively correlated with the OXTR protein/mRNA ratio suggests that miR-21-5p can inhibit the translation of OXTR and may be an important factor in limiting the levels of OXTR in the human autism brain." (PMID 26273428, 2015). "Nonetheless, genetic studies have mainly failed to associate the oxytocin gene with autism; however, several studies have reported an association with the oxytocin receptor gene (OXTR; NCBI Gene ID: 5021), although inconsistently." (PMID 25408912, 2014). "This raised the possibility that methylation of OXTR, as a mechanism of epigenetic silencing, might be involved more generally in the etiology of autism." (PMID 23734094, 2013). "Perhaps the most exciting finding to date related to the role of the OT system in the etiology of autism was the recent discovery of significant increases in DNA methylation in the promoter region of the OXTR gene in blood and brain samples from autistic individuals compared to controls." (PMID 23226454, 2012). "At the same time our findings suggest that the hypermethylated status of OXTR in autism, resulting in a decrease in OXTR expression, may more commonly contribute to the disorder." (PMID 19845972, 2009). "In summary, the data presented suggest that genomic deletion or aberrant methylation of OXTR may contribute to the development of autism." (PMID 19845972, 2009). "As one would hypothesize given their increased methylation of OXTR, the autism cases also showed statistically lower transcript levels of OXTR expression compared to the normal controls." (PMID 19845972, 2009). "Together, these data provide strong evidence for the role of OXTR and oxytocin signaling pathway in the etiology of autism and, for the first time, show that the epigenetic regulation of OXTR may be an important factor in the development of the disorder." (PMID 19845972, 2009). "Based on the CNV data within the OXTR deletion family, we hypothesized that a hemizygous deletion of OXTR may result in a reduction in the available levels of OXTR in utero and during development, ultimately leading to the development of autism." (PMID 19845972, 2009). "While the mechanism for the development of autism from a germ line deletion of OXTR versus epigenetic silencing of the gene in the temporal cortex may clearly be different, the effect on oxytocin signaling could be the same." (PMID 19845972, 2009). "Additionally, our analysis of expression levels of OXTR in the temporal cortex shows decreased levels of expression in individuals with autism as compared to controls matched for age and sex." (PMID 19845972, 2009). "To functionally correlate DNA methylation levels within the temporal cortex DNA and expression of OXTR from which the DNA was derived, we carried out quantitative PCR analysis of mRNA levels from the cortex tissue of four autism cases matched for age and sex and four controls." (PMID 19845972, 2009).
autism (continued). "Importantly, altered OXTR methylation levels have been found in autism and ADHD patients." (PMID 34576011, 2021). "In addition, relationships between the polymorphisms of the oxytocin receptor gene (OXTR) and social behaviors have been reported, including correlations of OXTR polymorphisms with trust and altruism and with mental disorders such as autism." (PMID 30633779, 2019). "Data from the Stanford study on the severity of autism and oxytocin blood levels in children, which have undergone normalizing mathematical operations, are compared with a normalized theoretical model based on very plausible considerations of autism severity and oxytocin receptor numbers." (PMID 31827587, 2019). "Beyond continuously developing knowledge about how OXTr and AVPr influence behaviors, researchers of today have devoted much attention to the roles these receptors play in the etiology of sex-biased neuropsychiatric disorders involving impairments on a social level, such as autism." (PMID 29487501, 2018). "A single case report describes a family in which a rare mutation in the oxytocin receptor was detected in an individual with ASD, and a recent meta-analysis suggests certain common genetic variants may be over represented in autism." (PMID 26441508, 2015). "Further analysis revealed that microRNA upregulation may have a very relevant impact on biological pathways involved in autism, both by targeting oxytocin receptor expression and targeting several gene ontology pathways that are relevant to autism, including synapse function and signal transduction." (PMID 26273428, 2015). "Relatedly, many molecular genetic studies have so far focused on the oxytocin receptor (OXTR) gene, repeatedly showing that variations in the OXTR are significantly associated with measures of empathy, as well as with difficulties in empathy and with autism and ToM." (PMID 26157401, 2015). "Additionally, OXTR is a candidate autism gene whose levels may be important for social development of offspring." (PMID 19845972, 2009). "A previous study has also reported a genotype × autism symptom interaction for SMG responses during face emotion recognition for rs2254298, rs2268491and rs53576 OXTR SNPs." (PMID 38553454, 2024). "Also, a meta-analyses study consisting of a large number of participants (N ≥ 17000 for rs53576 and N ≥ for rs2254298) failed to support the impact of these two OXTR gene variants on five domains of human functioning including biology, personality, social behavior, psychopathology, and autism." (PMID 26599592, 2015). "Therefore, we suggest that miR-21-5p may attenuate OXTR expression in the human autism brain." (PMID 26273428, 2015). "More recent studies have found positive linkage between the 3p25 chromosomal region containing the oxytocin receptor (OXTR) gene and autism." (PMID 23226454, 2012). "A previous study reported that oxytocin receptor knockout voles demonstrated autism-like behavior such as a lack of interest in social novelty." (PMID 35310938, 2022). "Our study did not detect any association between rs2254298 and ASD, which was similar to the conclusion of a meta-analysis: a solid role in autism has not been established for OXTR rs2254298." (PMID 28484366, 2017). "Because deletions encompassing OXTR have not been observed in other studies characterizing structural variation in autism such events appear to be rare." (PMID 19845972, 2009). "The most significant finding thus far from our analysis is a heterozygous deletion of the oxytocin receptor gene (OXTR) (MIM accession no.: 167055) in an individual with autism and his mother with putative obsessive-compulsive disorder (OCD)." (PMID 19845972, 2009). "Our analysis revealed a genomic deletion containing the oxytocin receptor gene, OXTR (MIM accession no.: 167055), previously implicated in autism, was present in an autism proband and his mother who exhibits symptoms of obsessive-compulsive disorder." (PMID 19845972, 2009).